U6 (U6 spliceosomal RNA )
Synonyms: LOC124904721
Gene: Small nuclear RNA gene on chromosome 1 (43,716,467 to 43,716,556, forward strand). Ensembl gene ENSG00000283414.
Gene Ontology:
Molecular function: U4 snRNA binding
Biological process: formation of quadruple SL/U4/U5/U6 snRNP; spliceosomal tri-snRNP complex assembly
Cellular component: U4/U6 x U5 tri-snRNP complex; U6 snRNP
Homologues: Orthologues: dog U6 (73% identical), guinea pig U6 (62% identical). Paralogues in human: RNU6-1209P (91% identical), RNU6-115P (90% identical), RNU6-1340P (90% identical), RNU6-16P (90% identical), RNU6-23P (90% identical), RNU6-454P (90% identical), RNU6-774P (90% identical), RNU6-86P (90% identical), RNU6-11P (89% identical), RNU6-1309P (89% identical), RNU6-235P (89% identical), RNU6-28P (89% identical), and 1289 more.